LINC00987 (long independently transcribed non-coding RNA 987)
Gene: Long non-coding RNA gene on chromosome 12 (9,144,848 to 9,261,503, forward strand). Ensembl gene ENSG00000237248.
Diseases named in the same sentence as LINC00987 in open-access papers:
LINC00987 is named in the same sentence as 23 diseases in open-access papers, as found by Europe PMC text mining. Sharing a sentence is not in itself a finding about the gene and the disease. The quoted sentences say what the papers report.
acute myeloid leukemia (3 papers, 2021 to 2023). Acute myeloid leukemia (AML) is a group of neoplasms arising from precursor cells committed to the myeloid cell-line differentiation. "Knockdown of LINC00987 suppresses acute myeloid leukemia progression by inhibiting the IGF2BP2‐mediated PA2G4 expression." (PMID 36606322, 2023). "A previous study found that LINC00987 expression was increased in patients with acute myeloid leukemia and osteosarcoma and was closely related to poor prognosis." (PMID 35201476, 2021).
lung adenocarcinoma (2 papers, 2022 to 2024). A carcinoma that arises from the lung and is characterized by the presence of malignant glandular epithelial cells. "Specifically, the progression of lung adenocarcinoma is induced by the downregulation of low methylation related LINC00987, which inhibits phosphorylation-mediated SND1 degradation." (PMID 39411134, 2024).
lung carcinoma (2 papers, 2022 to 2024). "The biological function of LINC00987 has also been studied in lung cancer." (PMID 39411134, 2024).
osteosarcoma (2 papers, 2021 to 2024). A usually aggressive malignant bone-forming mesenchymal neoplasm, predominantly affecting adolescents and young adults. "For example, LINC00987 binds to miR-376a-5p by competing with FNBP1 to promote osteosarcoma cell development." (PMID 38910243, 2024). "Recently, emerging studies had illustrated the oncogenic role of LINC00987 in breast cancer and osteosarcoma." (PMID 38910243, 2024). "This study was the first to report that miR-376a-5p expression was reduced in osteosarcoma cells and that silencing miR-376a-5p promotes osteosarcoma development and attenuates the anticancer effect of LINC00987 inhibition in osteosarcoma." (PMID 35201476, 2021). "A previous study found that higher LINC00987 expression was strongly correlated with the lower overall survival of osteosarcoma." (PMID 35201476, 2021). "Next, we focused on further investigating the role and regulatory mechanisms of LINC00987 to provide new references for treating osteosarcoma." (PMID 35201476, 2021). "In this study, the expression of LINC00987 in osteosarcoma cells was analyzed." (PMID 35201476, 2021). "LINC00987 was found to be upregulated in osteosarcoma cells." (PMID 35201476, 2021). "LINC00987 as a potential therapeutic target for osteosarcoma." (PMID 35201476, 2021). "This study focused on the mechanistic involvement of LINC00987 in osteosarcoma." (PMID 35201476, 2021). "FNBP1 protein levels were significantly increased in osteosarcoma cells, particularly in 143B and U2OS cells, compared to those in hFOB1.19 cells, which was similar with the expression trends of LINC00987." (PMID 35201476, 2021).
thyroid cancer (2 papers, 2021 to 2022). "In addition, FBLN5 expression was reduced by miR-27b-3p overexpression, suggesting that FBLN5 is the downstream target gene of LINC00987 in thyroid cancer." (PMID 36306007, 2022). "Furthermore, FBLN5 knockdown promoted the malignant progression of thyroid cancer cells by counteracting the effect of LINC00987." (PMID 36306007, 2022).
cutaneous skin melanoma (1 paper, 2021). "We demonstrated that LINC00987 and A2M could be consistently regarded as protective factors in BRCA, kidney renal clear cell carcinoma, LUAD, sarcoma (SARC), cutaneous skin melanoma (SKCM), and UCEC; however, both were revealed to be risk factors for mesothelioma (MESO)." (PMID 33987201, 2021).
tumor (3 papers, 2021 to 2024). "To further explore whether the immune-related LINC00987/A2M axis also affected tumor epithelial-mesenchymal transition and hypoxia, we analyzed the relationship between the five hypoxia-associated gene sets and the LINC00987/A2M axis in TCGA, GSE31210, and GSEnew cohorts." (PMID 33987201, 2021). "The ssGSEA scores of all five hypoxia-associated gene sets indicated that they were up-regulated in the low LINC00987 or A2M expression group, implying that the LINC00987/A2M axis facilitated tumor cell growth and proliferation under hypoxia." (PMID 33987201, 2021). "Comprehensive bioinformatic analysis showed that the LINC00987/A2M axis is a functional and effective tumor suppressor and biomarker for assessing the immune microenvironment and prognostic and therapeutic evaluations of LUAD." (PMID 33987201, 2021). "We thus found that the LINC00987/A2M axis might play an important role in regulating tumor stemness and tumor hypoxia." (PMID 33987201, 2021).
cancer (1 paper, 2021). A tumor composed of atypical neoplastic, often pleomorphic cells that invade other tissues. "As such, LINC00987 and A2M might be key factors in treatment strategies against these cancers." (PMID 33987201, 2021).
LINC00987 also shares sentences with these, for which no sentence is quoted: breast carcinoma (1 paper); cervical squamous cell carcinoma (1); diffuse large B-cell lymphoma (1); endocervical adenocarcinoma (1); esophageal carcinoma (1); lymphoid neoplasm (1); mesothelioma (1); ovarian serous cystadenocarcinoma (1); pancreatic adenocarcinoma (1); prostate adenocarcinoma (1); rectum adenocarcinoma (1); sarcoma (1); Sepsis (1); stomach adenocarcinoma (1); uveal melanoma (1).